ZNF17 (zinc finger protein 17)
Description:
May be involved in transcriptional regulation.
Synonyms: KIAA1947; KOX10; HPF3; FLJ40864; FLJ46058; FLJ46615
Tractability: PROTAC: ubiquitination databases record sites on it.
Gene: Protein-coding gene on chromosome 19 (57,410,723 to 57,421,934, forward strand). Ensembl gene ENSG00000186272.
Subcellular location: Nucleus
Pathways (Reactome):
Gene expression (Transcription): Generic Transcription Pathway
Gene Ontology:
Molecular function: protein binding; DNA-binding transcription factor activity, RNA polymerase II-specific; RNA polymerase II cis-regulatory region sequence-specific DNA binding
Biological process: regulation of transcription by RNA polymerase II; regulation of DNA-templated transcription
Cellular component: nucleus
Genetic constraint (gnomAD): Loss-of-function variants: 4 observed, 7.55 expected, observed/expected ratio (o/e) 0.53, 90% interval 0.26 to 1.21. That is too few expected variants to judge how well the gene tolerates losing a copy. Missense variants: 676 observed, 762.18 expected, observed/expected ratio (o/e) 0.89, 90% interval 0.83 to 0.94. Synonymous variants: 229 observed, 244.52 expected, observed/expected ratio (o/e) 0.94, 90% interval 0.84 to 1.04.
Homologues: Orthologues: chimpanzee ZNF17 (99% identical). Paralogues in human: ZNF416 (41% identical), ZNF530 (40% identical), ZNF547 (39% identical), ZNF587 (38% identical), ZNF417 (37% identical), ZNF776 (36% identical), ZNF287 (35% identical), ZNF34 (33% identical), ZKSCAN7 (33% identical), ZNF852 (32% identical), ZNF527 (32% identical), ZNF285 (31% identical), and 38 more.
Diseases named in the same sentence as ZNF17 in open-access papers:
ZNF17 is named in the same sentence as 1 disease in open-access papers, as found by Europe PMC text mining. Sharing a sentence is not in itself a finding about the gene and the disease.
ZNF17 shares sentences with these, for which no sentence is quoted: ciliopathy (1 paper).